LIN28B (lin-28 RNA binding posttranscriptional regulator B)
Diseases named in the same sentence as LIN28B in open-access papers (continued):
Sharing a sentence is not in itself a finding about the gene and the disease.
neuroblastoma (continued). "In neuroblastoma, the subset of cells expressing SOX6 shows minimal overlap with those expressing LIN28B, supporting a SOX6 mediated LIN28B downregulation in this context." (PMID 38704454, 2024). "At the molecular level, aggressive neuroblastoma tumor phenotypes correlate with a definite number of oncogene drivers, such as MYCN, ALK, and LIN28B." (PMID 38338881, 2024). "Similarly, another study determined the role of the Lin28B/let-7 pathway in regulating glycolytic metabolism, ATP production, and neurosphere formation in neuroblastoma (NB)." (PMID 36230562, 2022). "Lin-28 homolog B (LIN28B) is related to multiple human diseases, such as hepatocellular carcinoma, neuroendocrine prostate cancer, neuroblastoma and Ewing sarcoma." (PMID 34863268, 2021). "LIN28B cooperates with RANBP2 to promote RAN expression and activity of RAN GTPase, thereby driving the oncogenesis of neuroblastoma." (PMID 33816306, 2021). "Although LIN28B, DICER and other RNA-binding proteins (RBPs) have reported roles in neuroblastoma development and patient outcome, the role of RBPs in neuroblastoma is relatively unstudied." (PMID 32707690, 2020). "In this case, LIN28B, or LIN28B mutant that is unable to inhibit let-7 processing, increases the penetrance of MYCN-induced neuroblastoma, potentiates the invasion and migration of transformed sympathetic neuroblasts, and drives distant metastases in vivo." (PMID 33054808, 2020). "This is surprising, as LIN28B, perhaps the best characterised RBP in neuroblastoma, can induce neuroblastoma in mice and potentially in some rare human cases as well." (PMID 32707690, 2020). "Our current study, focused on LIN28B-PBK signaling, in conjunction with our previous discovery of a LIN28B-RAN-AURKA network, highlights two kinases that are downstream LIN28B/let-7 targets in neuroblastoma." (PMID 32923517, 2020). "For example, hepatoblastomas, Wilm’s tumors and most neuroblastomas present early in life, and they often express the oncofetal proteins LIN28 or LIN28B at high levels to help maintain the primitive differentiation states of their respective anlagen." (PMID 27879203, 2016). "Furthermore, expression of several genes associated with glioblastoma (STAT3, PDGFRA, MET, and NF1) and neuroblastoma (GATA3, ISL1, LMO1, and LIN28B) progression was downregulated at the transcriptional level in differentiated cells." (PMID 39859209, 2025). "Overexpression of LIN28B in neuroblastoma increases the levels of RAN by directly binding RAN mRNA, and then RAN induces phosphorylation of threonine 288 of AURKA and increases AURKA enzymatic activity, ultimately facilitating neuroblastoma progression." (PMID 39510185, 2024). "Apart from the mechanism in neuroblastoma, it has been shown that LIN28B overexpression did not induce brain tumor formation originating from Nestin-positive neural precursors." (PMID 37304235, 2023). "In neuroblastoma, DFMO has been found to reduce Lin28B protein and increase Let-7 miRNA levels." (PMID 33579942, 2021). "While our findings show that PBK lies downstream of both LIN28B and MYCN, and the functions of PBK mimic those of LIN28B in vitro, whether PBK sculpts neuroblastoma metastasis in the in vivo setting is unknown." (PMID 32923517, 2020). "Since LIN28B is involved in SCD in Drosophila intestine stem cells and Caenorhabditis elegans embryos, it may control the cell division fate in neuroblastoma cells in an evolutionarily conserved manner." (PMID 33194665, 2020). "Given the overlap between LIN28B and PBK in mediating self-renewal and migration, we hypothesize that both LIN28B and PBK promote neuroblastoma metastasis." (PMID 32923517, 2020). "Our current understanding of the oncogenic role of LIN28B in neuroblastoma tumor formation is that it is a negative regulator of the let-7 family of miRNAs that directly target MYCN." (PMID 29492199, 2018). "Focal aberrations affect genes known to be involved in neuroblastoma, such as ALK and LIN28B." (PMID 30375995, 2018).
neuroblastoma (continued). "Moreover, two novel bona fide neuroblastoma oncogenes have been identified, ALK and LIN28B, that are sufficient to drive tumor formation when overexpressed in the neural crest or seem to increase the oncogenic potential of MYCN overexpression." (PMID 29492199, 2018). "Also the few neuroblastoma driver genes that were identified so far, including MYCN, ALK, PHOX2B and LIN28B, are all involved in early stages of the sympathetic nervous system development with both LIN28B and MYCN implicated as major drivers of stemness." (PMID 30504901, 2018). "Lin28B, a specific substrate of TRIM71, has been reported to function as an oncogenic protein that promotes in vitro transformation of primary cells and tumorigenesis in various models of neuroblastoma, breast epithelial, and intestinal epithelial cancer." (PMID 27821801, 2016). "In addition, in neuroblastoma cell lines, SOX6 and LIN28B expression negatively correlate." (PMID 38704454, 2024). "However, LIN28B’s involvement in neuroblastoma cell metabolism has not been fully elucidated, but its broader impact on tumorigenesis suggests a complex interaction with metabolic pathways, similar to its role in other cancer types." (PMID 38338881, 2024). "In this way, LIN28B promotes transformation and migration in colon cancer through LGR5, PROM1, and CDX2 mRNAs, promotes stemness and EMT in gastric cancer through NRP-1 mRNA, inhibits apoptosis in ovarian cancer through AKT2 mRNA, and promotes migration in neuroblastoma through MYCN-induced mRNAs." (PMID 37370851, 2023). "However, a prolonged overexpression of LIN28B was not accompanied by a significant increase in glucose metabolism, suggesting that iLIN28B-level diversity enabled the formation of two distinct metabolic phenotypes in neuroblastoma cells." (PMID 38338881, 2024).
breast carcinoma (48 papers, 2013 to 2025). "Lin28B is also associated with the overexpression of breast cancer stem cells (CSCs), along with ALDH1 and OCT4, which increases tumorigenicity and invasiveness." (PMID 40647432, 2025). "The RBP LIN28B is associated with tumor development, invasion, and poor prognosis in various types of cancers, such as esophageal, colon, ovarian, prostate, and breast cancers." (PMID 37318881, 2023). "The impact of LINC00665 in induction of expression of LIN28B is associated with induction of progression of breast cancer and activation of epithelial–mesenchymal transition (EMT) program in these cells." (PMID 36429005, 2022). "High levels of LIN28A (or LIN28B, the second Lin protein) are associated with many human cancers such as glioblastoma, ovarian, gastric, prostate and breast cancers, as well as pediatric cancers." (PMID 34445617, 2021). "Interestingly, low pH in breast cancer caused by high levels of lactate increased cancer stemness as represented by LIN28B, Myc, and aldehyde dehydrogenase 1 (ALDH1) expression." (PMID 37304235, 2023). "It remains elusive whether LIN28B expression can favor a certain site of metastasis, since it has been previously functionally linked to lung and liver metastasis of breast cancer." (PMID 37304235, 2023). "Importantly, the lowered exosomal let-7s were further associated with breast cancer patients’ poor prognostic, suggesting that Lin28B mediates tumor progression via lower exosomal let-7s." (PMID 35173168, 2022). "Therefore, blocking of the LIN28B/MYC/miR-34a-5p signaling pathway, by the LIN28B specific inhibitor, causes a dramatic inhibition of tumor growth and metastatic potential in orthotopic immunodeficient mouse models of human breast cancer cells." (PMID 32486505, 2020). "This is consistent with previous studies in breast cancer and diabetic nephropathy models, where miR-379-5p was shown to suppress LIN28B expression and inhibit cell proliferation." (PMID 41427137, 2025). "Lin28B, an RNA-binding protein, contributes to breast cancer metastasis through multiple mechanisms, including the enhancement of cancer stem cell properties and the formation of a pre-metastatic niche through immunosuppression." (PMID 40647432, 2025). "Transcription factors like Lin28B and CCAAT/enhancer binding protein δ (C/EBPδ) also play important roles in the metastatic niche formation, whereas Lin28B is involved in lung metastases of breast cancer." (PMID 39858015, 2025). "In breast cancer, Lin28B facilitates metastasis to the lungs through recruiting neutrophils and promoting N2 neutrophil conversion by creating an immune‐suppressive premetastatic niche." (PMID 39611045, 2024). "Lin28B has been considered a potent inducer of breast cancer metastasis, and neutrophil N2 conversion is a key step in the suppression of T-cell function." (PMID 37534210, 2023). "Among four lncRNA, LINC00839 had been reported to promote breast cancer proliferation and chemoresistance via Lin28B‐mediated upregulation of Myc and activation of the PI3K/AKT pathway." (PMID 36426411, 2023). "In summary, Qi and coworkers here identified a new mechanism of LIN28B promoting breast cancer metastasis formation, which includes the creation of an immunosuppressive microenvironment in the secondary tumor site via tumor-delivered exosomes." (PMID 37304235, 2023). "This would then promote cancer progression, further strengthening the important oncogenic role of LIN28B in breast cancer." (PMID 37304235, 2023). "According to an analysis of a breast cancer cohort (463 cases, the Cancer Genome Atlas (TCGA), Nature 2012), LIN28B is upregulated in 15% of breast cancer patients." (PMID 37304235, 2023). "Here, we demonstrate that Lin28B promotes lung metastasis of breast cancer by building an immune-suppressive pre-metastatic niche." (PMID 35173168, 2022). "Here, we determine that Lin28B can establish immune suppression pre-metastatic niches to promote breast cancer lung metastasis." (PMID 35173168, 2022).
breast carcinoma (continued). "By the orthotopic breast cancer model, we determined that Lin28B was properly expressed in the primary tumors, which expression did not affect the primary tumor growth." (PMID 35173168, 2022). "Lin28B was found to control the aerobic glycolysis metabolic state and lower the microenvironment pH through the Lin28B/Myc/miR-34a-5p pathway in breast cancer stem cells (BCSCs)." (PMID 36230562, 2022). "Here the authors show that tumor-intrinsic Lin28B, a RNA-binding protein, has an essential role in the formation of an immune-suppressive pre-metastatic niche, promoting lung metastasis of breast cancer." (PMID 35173168, 2022). "While Lin28B is recognized as a breast cancer metastasis promoter, little is known about its detailed mechanism." (PMID 35173168, 2022). "Our study exposes a mechanism by which Lin28B dictates breast cancer metastasis through shaping immunosuppression in the metastatic lung niche." (PMID 35173168, 2022). "We also identify that breast cancer-released exosomes with low let-7s are a prerequisite for Lin28B-induced immune suppression." (PMID 35173168, 2022). "Given this, we suggested the enhanced effects of LINC00467 on the aggressiveness of breast cancer partly depended on the upregulation of protein level of LIN28B." (PMID 33996559, 2021). "As is the case for NFκB, the activation of STAT3 in breast cancer promotes the transcription of Lin28B by directly binding to the Lin28B promoter, resulting in the repression of let-7 expression and concomitant upregulation of the let-7 target, HMGA2." (PMID 34572067, 2021). "Despite this mechanism occurring in breast cancer cells, it is interesting to note that LIN28B overexpression promotes NB onset." (PMID 33921816, 2021). "Our findings suggest LINC00467 promotes progression of breast cancer through interacting with miR-138-5p and LIN28B directly." (PMID 33996559, 2021). "Taken together, these data indicated LINC00467 up-regulated the protein levels of LIN28B via a direct interaction in breast cancer cells." (PMID 33996559, 2021). "LINC00665, for example, is known to accelerate breast cancer progression via the miR-379-5p/LIN28B pathway." (PMID 34592879, 2021). "Collectively, our results reveal that the LINC00665–miR-379-5p–LIN28B axis is a critical player in breast cancer progression and a promising target for breast cancer therapy." (PMID 31907362, 2020). "In breast cancer cell lines, the inhibition of LIN28B suppresses MYC expression and increased miR-34a-5p levels expression, correlating with inhibition of glucose uptake/lactate production and a better patient’s prognosis." (PMID 32486505, 2020). "LINC00665 promoted breast cancer progression and induced an epithelial–mesenchymal transition-like phenotype via the upregulation of LIN28B expression." (PMID 31907362, 2020). "Together, our study reveals that the LINC00665–miR-379-5p–LIN28B axis in breast cancer and provide a novel mechanism explaining breast cancer progression." (PMID 31907362, 2020). "The activation of NF-κB by CCL18 results in an increase in the expression of Lin28b in breast cancer cells." (PMID 33114763, 2020). "This pathway causes the activation of NF-κB, which produces an increase in the expression of Lin28b in breast cancer cells." (PMID 33114763, 2020). "Further analysis showed a negative correlation between both onco-proteins, this result is similar as previous report in which Lin28A and Lin28B is reversely expressed in breast cancer." (PMID 27793004, 2016). "Our previous studies showed that CCL18 activates the PyK2-Src-FAK-ERK/PI3K signaling cascade in breast cancer cells, while N-Ras and Lin28b locate upstream and downstream, respectively, of this cascade." (PMID 26244871, 2015). "Our present study has shown that CCL18 reduces the expression of miR98 and miR27b in breast cancer cells via the N-Ras/ERK/PI3K/AKT/NFκB/Lin28b signaling cascade." (PMID 26244871, 2015).
breast carcinoma (continued). "Western blot analysis indicated that transfection with miR98, but not the mock or negative control, inhibited the activation of the N-Ras/ERK/PI3K/NFκB/Lin28b signaling pathway induced by CCL18 in breast cancer cells." (PMID 26244871, 2015). "In our present study, miR-27b abrogated CCL18-induced migration and invasion of breast cancer cells by silencing Lin28b, and led to increased mature miR98 to block CCL18 signaling." (PMID 26244871, 2015). "Furthermore, low exosomal let‐7s generated by breast cancer cells are necessary for Lin28B‐induced immune suppression." (PMID 39611045, 2024). "A further study wherein the previous author was also involved, demonstrated that LIN28B overexpression could diminish the inhibiting effects of metformin on the breast cancer cell transformation, and thus can contribute to therapy resistance." (PMID 37304235, 2023). "It has been reported that the LIN28A and LIN28B genes are reactivated in many human malignancies, such as breast cancer, colon cancer, lung cancer, ovarian cancer and hepatocellular carcinoma (HCC), and their expression is correlated with poor clinical disease outcomes." (PMID 34548635, 2022). "Therefore, with Lin28B expression, a breast cancer cell subset with BCSCs properties is vital to drive immune suppression and predicts poor prognosis." (PMID 35173168, 2022). "Moreover, we show that Lin28B induces primary tumors to produce more ALDH+ breast cancer stem cells (BCSCs), the principal source for tumor exosomes with low let-7s." (PMID 35173168, 2022). "LIN28B overexpression has been reported to induce EMT changes in breast cancer cell lines." (PMID 34548635, 2022). "In this work, we seek to explore the mechanism by which Lin28B promotes breast cancer metastasis." (PMID 35173168, 2022). "Accordingly, interfering with neutrophils’ N2 conversion may be an accessible way to inhibit Lin28B-mediated breast cancer lung metastasis." (PMID 35173168, 2022). "Together, these findings suggested a role of Lin28B in promoting breast cancer lung metastasis." (PMID 35173168, 2022). "Thus, our results indicate that IL-6- and IL-10-mediated neutrophil N2 conversion is a key mechanism to promote lung metastasis of breast cancer in the context of Lin28B expression." (PMID 35173168, 2022). "Lin28B promotes breast cancer progression by increasing tumor stemness, migration, and invasion." (PMID 35173168, 2022). "Lin28B induces primary tumors to produce more acetaldehyde dehydrogenase (ALDH) breast cancer stem cells (BCSCs), which release tumor exosomes containing low let-7s, the latter causes Lin28B to induce neutrophil infiltration and N2 transformation to establish the pre-metastatic niche (PMN)." (PMID 36005690, 2022). "Moreover, the lower let-7a expression also predicted reduced lung metastasis-free survival, implying the existence of a similar mechanism whereby Lin28B promotes human breast cancer progression via lower exosomal let-7s." (PMID 35173168, 2022). "Recent studies indicate that Lin28B could increase breast cancer stem cell population, a major source of low let-7 exosomes." (PMID 36430471, 2022). "In addition, LINC00665 contributes to breast cancer development via modulating miR-379-5p and LIN28B." (PMID 33407473, 2021). "LIN28B has been broadly proved to play a critical oncogenic role in breast cancer." (PMID 33996559, 2021). "Similarly, activation of the STAT3/NFκB pathway in breast cancer cells by M1 macrophage secreted pro-inflammatory cytokines elicits Lin28B-let-7-HMGA2 axis to induce CD44+/CD24- and ALDH1+ CSCs through activation of EMT." (PMID 34572067, 2021). "Besides, LIN28B was also reported to promote proliferation of breast cancer cells via HBXIP-induced activation of TF II D." (PMID 33996559, 2021). "We next investigated whether LINC00665 regulates breast cancer progression by regulating LIN28B expression." (PMID 31907362, 2020).